CD80 (CD80 molecule)
Diseases named in the same sentence as CD80 in open-access papers (continued):
Sharing a sentence is not in itself a finding about the gene and the disease.
tumor (continued). "Accumulating evidence indicates that tumor immune microenvironment (particularly regarding PD-1, PD-L1/2, forkhead box P3 (Foxp3), CD80, and CD86 expression) and immune checkpoint signaling play decisive roles in tumor immune evasion and growth." (PMID 36483592, 2022). "In tumor tissues of patients suffering from recurrent disease in the follow-up period, CD80 was significantly downregulated (p = 0.02, FC = −2.2)." (PMID 35406584, 2022). "On the other hand, tumor cells also reduce the expression of CD80 and CD86 and increase the expression of inhibitory molecules such as PDL-1, which neutralizes TIL-dependent antitumor responses." (PMID 36389779, 2022). "Durvalumab is a high-affinity humanized IgG1 monoclonal antibody targeting PD-L1 that blocks the binding of PD-L1 to PD-1 and CD80/B7.1, restores the immune response, and kills tumor cells." (PMID 36092724, 2022). "On the other hand, we observed an elevation in the relative abundance of M2 macrophages (CD206+CD80−) in tumor following RT alone, but this effect was reduced when RT was combined with PIC injection." (PMID 35999216, 2022). "Especially, regulatory T cells were significantly reduced in the TC1 tumor model and there was an increase in central memory cytotoxic T cell infiltration and an increased proportion of macrophages with high CD80 expression in the C3PQ tumor model." (PMID 35356198, 2022). "Analysis of the stromal compartment in primary tumor specimens revealed that the expression of NF1 (HR = 0.748, p = 0.025), CD27 (HR = 0.279, p = 0.035), and CD80 (HR = 0.703, p = 0.02) was associated with a better OS." (PMID 35651606, 2022). "Interaction between PD-L1 present on cancer cells or tumor-infiltrating immune cells and its receptors PD-1 and B7-1 (also known as CD80) on T cells delivers a signal that inhibits the activation of T cells." (PMID 34230534, 2021). "Here, we showed that CD80 deactivation in tumor cells affected the pro-/anti-tumorigenic role of distinct immune cell populations." (PMID 33923750, 2021). "One mechanism by which Treg suppress the anti-tumor response is by interaction of CTLA-4 with CD80/CD86 on DC leading to a reduced expression of MHC class II, CD40 and CD86 molecules, all being important for Treg maturation and activation." (PMID 34638420, 2021). "These tumor-infiltrating MHC class IIhigh DCs derived from AAA-CD4+ T cell-treated mice expressed high levels of CD80 and CD86 on their surface." (PMID 34625113, 2021). "Atezolizumab, a fully humanized mAb, targets PD-L1 and blocks its interactions with PD-1 and B7.1 (CD80) to restore the anti-tumor immune responses." (PMID 33522929, 2021). "When depleted of external H2O2, moDCs (CAT-DCs) express reduced levels of CD80/86, co-stimulatory molecules that play a crucial role in the induction and maintenance of T-cell activity and anti-tumor immunity." (PMID 33530408, 2021). "The immunosuppressive role of tumor-cell-expressed CD80 should be considered in research into biomarkers for the prediction of cancer patients’ sensitivity to immune checkpoint inhibitors and for the development of a tumor-cell-specific CD80 blockade." (PMID 33923750, 2021). "In the midst of T cells activated by microbeads, downregulation of CD80 was observed only on intratumoral MPs, while DCs in tumor and colon retained their CD80 levels." (PMID 34680397, 2021). "CD80 is one of the most potent costimulatory molecules involved in tumor cell recognition and killing, is activated by CD28 or CTLA-4 binding, and can induce T cell proliferation and cytokine production." (PMID 34852825, 2021). "In this regard, the opposed expression of PD-1 and CD69 on specific T cells, as well as CD80 and PD-L1 on APCs in tumor vs. colon tissue, suggest discrete activation patterns in these tissues." (PMID 34680397, 2021).
tumor (continued). "To investigate the impact of the CD80 deactivation in tumor cells on anti-tumor immune reactions, we depleted CD4+, CD8+, natural killer (NK) 1.1+ cells, or macrophages in mice bearing TC-1- and TC-1/dCD80-1-induced tumors." (PMID 33923750, 2021). "The expression pattern of CD80 and PD-L1 in tumor and colon suggests that APCs within these discrete tissue environments have discrepancies in their capacity to promote and limit T cell activation." (PMID 34680397, 2021). "In vivo, CD86 was significantly increased on dendritic cells found in the spleen, and CD80 was increased significantly on dendritic cells in both spleen and tumor draining lymph nodes." (PMID 34136405, 2021). "For other CD80/CD86-negative solid tumors, it is worthy of consideration to utilize CAR construct targeting the tumor-associated antigens as well as converting CTLA4 signals." (PMID 33868277, 2021). "Here, we determined the immunosuppressive role of CD80 in the tumor microenvironment by CRISPR/Cas9-mediated deactivation of the corresponding gene in the mouse oncogenic TC-1 cell line." (PMID 33923750, 2021). "The CD80 deactivation switched the pro-tumor role of macrophages observed in TC-1-induced tumors to anti-tumor abilities in TC-1/dCD80-1-induced tumors." (PMID 33923750, 2021). "The tumour-draining lymph nodes (TDLNs) of the treated mice were collected to investigate the DC maturation by flow cytometric analysis of CD80+ and CD86+, two biomarkers of mature DCs51." (PMID 33893275, 2021). "Inhibitory immune marker (HAVCR2) and activating immune receptors (CD80, TNFRSF4, and TNFRSF9) were both at higher levels in the high-risk group, suggesting a complex immune microenvironment within the tumor." (PMID 33850474, 2021). "We also analyzed the M2-like phenotype of TAMs by detecting CD206-positive cells in spleens and CD206/CD163/CD86/CD80-positive cells in tumor tissues." (PMID 33537094, 2021). "The expression of CD80/CD86 on tumor cells and immunosuppressive cells with the TME, such as MDSCs, makes the CTLA4-CD80/CD86 axis a remarkable target for cancer immunotherapies." (PMID 33868277, 2021). "This study contributed to the research into predictive markers to select patients who are suitable for immune checkpoint blockade therapy and suggested the development of a novel cancer immunotherapy based on a tumor-cell-targeted CD80 blockade." (PMID 33923750, 2021). "Consistently, our in vivo data show that Poly6 vaccination also led to a strong enhancement of CD40 expression in tumor infiltrated DCs compared to other DC costimulatory molecules (CD80, CD86, and MHC class II)." (PMID 33499256, 2021). "The identification of sEV‐carried PD‐L1 further expands the potential application of WJMSC‐derived sEVs for their anti‐tumour therapy through PD‐L1/CD80 checkpoint regulation." (PMID 33598108, 2021). "DCs have been shown to activate Tregs as well as Th17 cells in MM and promote tolerance to tumor antigens and T-cell evasion via interactions of CD80/CD86 with CD28 on tumor cells." (PMID 33717170, 2021). "In line with that report, CD80 deactivation in TC-1 cells reduced tumor formation and growth in our study." (PMID 33923750, 2021). "Durvalumab, a human monoclonal antibody (MAb), functions as an immune checkpoint inhibitor by blocking the binding of PD-L1 to its receptors, PD-1 and CD80 (B7-1), in order to reactivate tumor-specific T-cell response and enhance antitumor activity." (PMID 34580336, 2021). "Relative to internal DQ-OVA- control, there was a significant downregulation of CD86 on DQ-OVA+ MPs in the tumor, while upregulation of CD80 was observed on DQ-OVA+ colonic MPs." (PMID 34680397, 2021). "CD80 is a classical activation marker in myeloid cells, which is broadly down-regulated in tumor-infiltrating subsets." (PMID 34208043, 2021).
tumor (continued). "The tumor cells with deactivated CD80 (TC-1/dCD80-1) were more immunogenic than parental cells and induced tumors that gained sensitivity to cytotoxic T-lymphocyte antigen 4 (CTLA-4) blockade, as compared with the TC-1 cells." (PMID 33923750, 2021). "As CD14+ MPs were the predominant MP subset, their inversed pattern of CD80 and PD-L1 expression in tumor and colon remained unchanged." (PMID 34680397, 2021). "CD80 expression on TC-1 tumor cells affected the tumor microenvironment and sensitivity to immunotherapy." (PMID 33923750, 2021). "For optimal cytotoxic T cell-mediated tumor response, co-stimulation by CD80/CD86 binding to CD28 is required." (PMID 33802033, 2021). "Experiments in a murine model revealed that T cell costimulatory molecules such as CD80/CD86 are increased in tumor infiltrating immune cells after cisplatin treatment, suggesting that CD80/CD86 expression can be modulated by cisplatin treatment." (PMID 33802033, 2021). "DC immune functions are impaired both in the circulation and at tumor sites in patients with EC, and this is accompanied by decreased CD80 and CD86 expression." (PMID 33995371, 2021). "The expression of CD80 and CD86, two CTLA4 ligands, were observed in ATLL cells and tumor-associated stromal cells." (PMID 33918793, 2021). "Next, we evaluated the effect of CD80 deactivation in tumor cells and immune checkpoint blockade on the expression of Treg markers by the automatically generated Treg subpopulations." (PMID 33923750, 2021). "Surprisingly, we observed that CD80 deactivation in tumor cells markedly enhanced infiltration by NK and NKT cells, although the depletion of NK1.1+ cells did not affect TC-1/dCD80-1-induced tumor growth." (PMID 33923750, 2021). "Durvalumab is a humanized IgG1 mAb with high affinity targeting PD-L1 that selectively blocks the binding of PD-L1 to PD-1 and CD-80/B7-1, thus enabling T cells to recognize and kill tumor cells." (PMID 34745958, 2021). "Deactivation of CD80 in tumor cells approximately doubled the infiltration of CD45+ cells, but the proportion of T lymphocytes was not substantially altered." (PMID 33923750, 2021). "Several trials have also been performed with the monoclonal antibody atezolizumab which prevents the interaction of PD‐L1 with PD‐1 and B7.1 (CD80), which in turn causes less suppression of tumor‐reactive lymphocytes." (PMID 33314633, 2021). "An integrated gene profile and functional analysis of tumor-infiltrating immune cell (TIC) proportions revealed that DC activation markers (CD80, CD83, CD86) were positively correlated with CXCL8 expression." (PMID 34025668, 2021). "The distinct milieus of tumor and colon are likely reflected on the opposed expression of CD80 and PD-L1 on MPs, as well as PD-1 and CD69 on CD8+CD103+CD39+ T cells." (PMID 34680397, 2021). "In this study, we consistently observed high expression of both HLA-DR and CD40 by most tumor-infiltrating B cells, as well as CD80, CD83, and CD86 expression by a subset of B cells." (PMID 33763071, 2021). "Co-inhibitory CTLA-4 competes with co-stimulatory CD28 to bind to CD80 or CD86 on the surface of APCs to alleviate the anti-tumor immunity of tumor infiltrated T lymphocytes (TILs), such as CD4+T, CD8+T cells and regulatory T cells (Tregs)." (PMID 34858835, 2021). "Regarding the various interacting partners of CD80, with their broad range of effects on anti-tumor immune responses, the role of CD80 in the tumor microenvironment and its impact on the efficacy of cancer therapy need to be elucidated." (PMID 33923750, 2021). "To examine the in vivo anti-tumor activity of CTLA4-T cells toward CD80/CD86-expressing tumors, we developed subcutaneous xenograft models using NOD/SCID/IL2Rg−/− mice." (PMID 33868277, 2021). "B16-OVA tumor-bearing mice subcutaneously injected with CD80/OVA NP exhibited smaller average tumor sizes, longer survivals, and more desirable prophylactic efficacy." (PMID 34099630, 2021).
tumor (continued). "The efficacy of anti-CTLA-4, anti-PD-1, and anti-PD-L1 therapies is correlative to the levels of expression of CTLA-4, CD80/86, PD-1, and PD-L1 in the patients’ tumor cells, APCs, and T cells." (PMID 34136405, 2021). "Furthermore, tumor cells can escape the anti-cancer immunity by activating regulatory T lymphocytes that express cytotoxic T-lymphocyte-associated protein 4 (CTLA-4) competing with CD28 of effector T lymphocytes for binding to CD80/CD86 of antigen presenting cells." (PMID 32610582, 2020). "Flow cytometry analysis demonstrated a decrease of M2-type macrophages (CD206+CD11b+F4/80+) and an increase of M1 ones (CD80+CD11b+F4/80+) within the tumor." (PMID 32999291, 2020). "Collectively, the results of these data indicate that the addition of this adjuvant has a robust effect on the antigen-specific T cell response and CD80-Fc reduces tumor burden in a syngeneic mouse tumor model." (PMID 32161596, 2020). "Although the mechanistic signaling pathways remain elusive, FAK inhibition induced tumor regression of CD80-expressing tumors by increasing the CD28+ T cell population within the TME." (PMID 32514188, 2020). "DCs isolated from several tumor models and cancer patients were found to possess tolerogenic properties, such as low levels of co-stimulatory molecules (CD80, CD86) and low production of Th1-polarizing cytokine IL-12." (PMID 33105813, 2020). "CTLA-4 is a co-inhibitory receptor associated with suppression of anti-tumor immune responses and has a higher affinity than CD28 for binding CD80." (PMID 31959281, 2020). "Cells expressing CD80 can induce cytotoxic T cell activation through association with CD28, a T cell costimulatory receptor, which promotes tumor clearance." (PMID 32514188, 2020). "In the tumor microenvironment, DCs express both PD-L1 and CD80, with the amount of PD-L1 greatly exceeding that of CD80." (PMID 32992658, 2020). "Additional studies have verified that DEX activates CD8+ and CD4+ T cells and induces an anti-tumor immune response by exosomal CD80 and endogenous IL-2 in vivo." (PMID 33183286, 2020). "Durvalumab blocks PD‐L1 binding to PD‐1 and CD80, allowing T cells to recognize and kill tumor cells." (PMID 33103845, 2020). "(E) Left - Subcutaneous tumor growth of SCC7.1 cells treated with either Vehicle or 50 mg/kg BI 853520 ± 100 μg anti-CD80 antibody." (PMID 31959281, 2020). "Lastly, we sought to determine the relevance of the addition of CD80-Fc with the STEAP1 vaccine in a tumor challenge model." (PMID 32161596, 2020). "We provide evidence that macrophage-driven ICB resistance is established by CD4 T cell suppression and Treg expansion in the tumor microenvironment via the PD-L1/PD-1/CD80 axis." (PMID 32071302, 2020). "The B lymphoid tumor cell expresses class II MHC (Major Histocompatibility Complex) and the CD80/86 co-stimulation molecules which are functionally active and allow the tumor lymphocyte to act as an APC." (PMID 33381116, 2020). "A study of 150 patients of Spanish cohort demonstrated that CD163+ macrophages were found in tumor invasive front while CD80+ cells located in adjacent normal mucosa in less invasive T1 colorectal cancer that was detected by immunohistochemistry." (PMID 33194645, 2020). "Attempts to more broadly define the extent of cancer cell CD80 expression using bulk tumor transcriptomics data, for example using the Cancer Genome Atlas (TCGA), are confounded by the fact that CD80 is also expressed by infiltrating antigen presenting cells." (PMID 31959281, 2020). "RNA profiling of microenvironment-related genes revealed increased expression of markers for TAMs and resident microglia (Aif1, Itgam, Cd68 and Cx3cl1), and macrophage M1/M2 polarisation (Cd80 vs. Cd163) in knockdown tumours." (PMID 33339831, 2020). "Of note, the inability of PD-L1 to bind CD80 in cis resulted in attenuated immune responses, including anti-tumor responses." (PMID 32992658, 2020).
tumor (continued). "We confirmed the high expression of CD80 on tumor Tregs at the protein level by FACS, but not in the I-TDLN because of the high variability among patients." (PMID 32601304, 2020). "In order to gain more insight in the expression of PD-L1 and PD-L2 in relation to CD80 on infiltrating immune cell populations, we performed additional comprehensive flow cytometric analyses on tumor digests of 7 SCC and 3 AC." (PMID 33424844, 2020). "In this article, we reveal two different methods for enhancing anti-tumor T cell responses to synthetic DNA vaccines: indirectly via Flt3L and directly via CD80." (PMID 32161596, 2020). "In a skin cancer model for squamous cell carcinoma that responds to adoptive T-cell transfer, TGF-β-responding tumor stem cells selectively expressed CD80, a surface ligand previously identified on immune cells." (PMID 32380703, 2020). "The best characterized pathways are the interactions between CTLA-4 and CD80/86, and the binding of PD-1 to PD-L1 to tumor cells." (PMID 32602545, 2020). "We show that a FAK inhibitor can shift this balance in favor of CD80 - CD28 interaction, promoting an anti-tumor immune response that is dependent on both CD80 and CD28." (PMID 31959281, 2020). "The frequency of CD80+CD86+ mature BMDCs after co-culture with 4T1 tumour cells pretreated with free OLE was significantly higher that of the control group, indicating that ICD from dying 4T1 cells elicited by OLE can induce DC maturation and immune response." (PMID 33009382, 2020). "Briefly, the binding of CD28 on T cells to B7-1/B7-2 (CD80/CD86) on antigen-presenting cells (APC) results in co-stimulatory anti-tumor responses." (PMID 33182298, 2020). "The interaction between tumor PD-L1 and its receptors, PD-1 and CD80 on the surface of cytotoxic T cells, is responsible for the neutralization of anti-tumor immune responses." (PMID 32824655, 2020). "Our results are in line with previous studies showing increased tumor cell uptake and upregulation of maturation markers CD80 and CD86 on different subsets of human blood DCs after treatment with CDDP and OXA." (PMID 32560232, 2020). "Beyond the adenosine pathway, CD80 expression on tumor stem cells responsive to transforming growth factor-β (TGF-β) was identified as the primary cause of relapse after adoptive T-cell transfer." (PMID 32380703, 2020). "This study revealed that after two weeks of tumor‐bearing, a higher percentage of spleen antigen‐presenting cells (CD11c+, HLA+, CD80+, and CD11b+) was observed in the iPSC+CpG group." (PMID 32314522, 2020). "Immune checkpoint receptors, including PD-1 and CTLA4, are expressed on the surface of immune cells, whereas the cognate ligands (PD-L1/PD-L2 and CD86/CD80) are expressed on the tumor cell surface." (PMID 33425739, 2020). "Here, a population of tumor-initiating cells responsive to TGF-β acquires the expression of CD80 (a molecule previously identified on cells of the immune system) and hinders cytotoxic T cell activity leading to tumor relapse." (PMID 31355143, 2019). "PD-L1, a transmembrane protein expressed on tumor cells, upon binding to PD-1 and CD80 reduces anti-tumor T-cell activity." (PMID 31894921, 2019). "CD80 is expressed mainly on the surface of professional antigen-presenting cells (APCs) but is sometimes detected at low levels on tumor cells." (PMID 31112530, 2019). "Whereas, CD80−PD-L1+ human tumor cells anergized activated PD-1+ human PBMC and inhibited their production of IFNγ, CD80+PD-L1+ human tumor cells prevented anergy and maintained IFNγ production." (PMID 31001479, 2019). "We have previously shown that single agent B10G5 enhances DC activation in tumor draining lymph nodes and increases the expression of DC co-stimulatory molecule CD80 and CD86." (PMID 31446896, 2019).